C16orf78 (chromosome 16 open reading frame 78)
Synonyms: MGC33367
Tractability: PROTAC: ubiquitination databases record sites on it.
Gene: Protein-coding gene on chromosome 16 (49,373,804 to 49,399,431, forward strand). Ensembl gene ENSG00000166152.
Subcellular location (Human Protein Atlas): Connecting piece; End piece; Mid piece; Principal piece
Gene Ontology:
Cellular component: nucleus
Genetic constraint (gnomAD): Loss-of-function variants: 19 observed, 27.29 expected, observed/expected ratio (o/e) 0.7, 90% interval 0.49 to 1.02. The upper end of that interval is the gene's LOEUF score, 1.02, which puts it in group 4 of 6, group 1 being the genes least tolerant of losing a copy. Missense variants: 339 observed, 342.38 expected, observed/expected ratio (o/e) 0.99, 90% interval 0.9 to 1.08. Synonymous variants: 130 observed, 116.74 expected, observed/expected ratio (o/e) 1.11, 90% interval 0.96 to 1.29.
Homologues: Orthologues: chimpanzee C16H16orf78 (98% identical), macaque C20H16orf78 (89% identical), pig C16orf78 (60% identical), rabbit C16orf78 (60% identical), dog C16orf78 (57% identical), mouse 4933402J07Rik (53% identical), rat C19h16orf78 (51% identical).
Diseases named in the same sentence as C16orf78 in open-access papers:
C16orf78 is named in the same sentence as 1 disease in open-access papers, as found by Europe PMC text mining. Sharing a sentence is not in itself a finding about the gene and the disease.
C16orf78 shares sentences with these, for which no sentence is quoted: tumor (1 paper).